VPS53 (VPS53 subunit of GARP complex)
Description:
Acts as a component of the GARP complex that is involved in retrograde transport from early and late endosomes to the trans-Golgi network (TGN). The GARP complex is required for the maintenance of the cycling of mannose 6-phosphate receptors between the TGN and endosomes, this cycling is necessary for proper lysosomal sorting of acid hydrolases such as CTSD. Acts as a component of the EARP complex that is involved in endocytic recycling. The EARP complex associates with Rab4-positive endosomes and promotes recycling of internalized transferrin receptor (TFRC) to the plasma membrane.
Synonyms: PP13624; FLJ10979; HCCS1; PCH2E; hVps53L
Tractability: Antibody: UniProt places it where antibodies can reach, with high confidence. PROTAC: ubiquitination databases record sites on it; its protein half-life has been measured.
Gene: Protein-coding gene on chromosome 17 (508,503 to 721,717, reverse strand). Ensembl gene ENSG00000141252.
Subcellular location: Golgi apparatus, trans-Golgi network membrane; Endosome membrane; Recycling endosome
Subcellular location (Human Protein Atlas): Golgi apparatus; Vesicles; Cytosol
Pathways (Reactome):
Vesicle-mediated transport: Retrograde transport at the Trans-Golgi-Network
Gene Ontology:
Molecular function: protein binding
Biological process: endocytic recycling; lysosomal transport; retrograde transport, endosome to Golgi; cytosolic transport; protein targeting to lysosome; vesicle-mediated cholesterol transport; vesicle-mediated transport
Cellular component: EARP complex; endosome membrane; GARP complex; Golgi apparatus; membrane; perinuclear region of cytoplasm; recycling endosome; trans-Golgi network membrane; cytosol
Genetic constraint (gnomAD): Loss-of-function variants: 67 observed, 106.21 expected, observed/expected ratio (o/e) 0.63, 90% interval 0.52 to 0.77. The upper end of that interval is the gene's LOEUF score, 0.77, which puts it in group 3 of 6, group 1 being the genes least tolerant of losing a copy. Missense variants: 911 observed, 1,077.6 expected, observed/expected ratio (o/e) 0.85, 90% interval 0.8 to 0.89. Synonymous variants: 409 observed, 405.74 expected, observed/expected ratio (o/e) 1.01, 90% interval 0.93 to 1.09.
Homologues: Orthologues: chimpanzee VPS53 (99% identical), macaque VPS53 (99% identical), dog VPS53 (98% identical), guinea pig VPS53 (98% identical), mouse Vps53 (97% identical), pig VPS53 (97% identical), rabbit VPS53 (94% identical), rat Vps53 (91% identical), zebrafish vps53 (90% identical), tropical clawed frog vps53 (89% identical), Drosophila melanogaster Vps53 (51% identical), Caenorhabditis elegans vps-53 (36% identical).
Diseases named in the same sentence as VPS53 in open-access papers:
VPS53 is named in the same sentence as 26 diseases in open-access papers, as found by Europe PMC text mining. Sharing a sentence is not in itself a finding about the gene and the disease. The quoted sentences say what the papers report.
pontocerebellar hypoplasia type 2E (4 papers, 2015 to 2025). Any non-syndromic pontocerebellar hypoplasia in which the cause of the disease is a mutation in the VPS53 gene. "Case 1103: The two variants in trans in the VPS53 gene (NM_018289.3) a c.1429 C > T (p.Arg477*) and a c.1716 T > G (p.Ser572Arg), are associated with Pontocerebellar hypoplasia, type 2E." (PMID 40593860, 2025). "Heterozygous mutations in Vps53 have been associated with pontocerebellar hypoplasia type 2E (PCH2E) and thus with mental retardation, microcephaly, spastic quadriplegia, and early onset seizures." (PMID 26539077, 2015). "However, mutations in Vps53 have been linked to the seizure phenotypes observed in pontocerebellar hypoplasia type 2E (PCH2E) suggesting that seizures may be associated with disruption of the GARP complex." (PMID 34712272, 2021).
microcephaly (3 papers, 2015 to 2024). A congenital or acquired developmental disorder in which the circumference of the head is smaller than normal for the person's age and sex. "Many affected genes participated in brain-related diseases or disorders; for example, inactivation of PNKP causes brain dysplasias, such as microcephaly and cerebellar atrophy, while VPS53 is associated with cerebral and cerebellar atrophy." (PMID 30930929, 2019). "Mutations in one component of the GARP complex, VPS53, cause PCCA2, a severe neurodegenerative disease characterized by profound mental retardation, progressive microcephaly, spasticity, and early-onset epilepsy." (PMID 26357016, 2015).
prostate carcinoma (3 papers, 2019 to 2021). A carcinoma that arises from epithelial cells of the prostate gland. "In brief, the results indicate that the rs684232 site and the target genes VPS53, FAM57A, and GEMIN4 are positively associated with prostate cancer cell malignancy, and the high expression for the three genes are associated with poor prognosis for cancer patients." (PMID 34445492, 2021). "Patients with higher expression of VPS53, FAM57A, and GEMIN4 exhibited worse disease-specific survival probability, as demonstrated in the Kaplan–Meier survival analysis on the TCGA prostate cancer cohort." (PMID 34445492, 2021). "We found that patients with higher expression levels of VPS53 (Log-rank p = 0.03), FAM57A (Log-rank p = 0.018), and GEMIN4 (Log-rank p = 0.016) had worse prostate cancer-specific survival probability." (PMID 34445492, 2021). "The results indicate that all three rs684232 target genes, VPS53, FAM57A, and GEMIN4, play essential roles during cell proliferation and colony formation of prostate cancer cells." (PMID 34445492, 2021). "The risk allele diminishes androgen receptor (AR) occupancy, is associated with decreased H3K27ac levels, and downregulates the expression of VPS53, FAM57A, and GEMIN4, and the knockdown of VPS53, FAM57A, and GEMIN4 in prostate cancer cells results in an increase in cell viability." (PMID 33919522, 2021). "The results indicate that the three target genes VPS53, FAM57A, and GEMIN4 may have a very important regulatory role in prostate cancer disease, and there may also be a synergistic promoting effect between them." (PMID 34445492, 2021). "Interestingly, we also found that downregulation of VPS53, GEMIN4, and FAM57A genes led to shorter disease-free intervals for prostate cancer patients to the contrary." (PMID 34445492, 2021). "For one of the regulatory SNPs, rs684232, we found that the variation altered chromatin binding of transcription factor FOXA1 on the DNA region and led to aberrant gene expression of VPS53, FAM57A, and GEMIN4, which play vital roles in prostate cancer malignancy." (PMID 34445492, 2021).
colorectal cancer (2 papers, 2019 to 2022). A primary or metastatic malignant neoplasm that affects the colon or rectum. "VPS53 expression is strongly reduced and positively correlates with the expression of the autophagy-related gene Beclin1 in colorectal cancer tissue." (PMID 35805075, 2022). "Although the molecular mechanisms underlying the VPS53-mediated regulation of the autophagy signaling pathway have not been revealed yet, these findings suggest that VPS53 is a tumor suppressor of colorectal cancer progression." (PMID 35805075, 2022). "Finally, we found that SMARCA5, MBD3, VPS53, EHD4 are estimated to mediate the regulation of miR-4701-3p and miR-4793-3p on colorectal cancer cell apoptosis, which targets ATP-dependent chromatin remodeling pathway and endocytic recycling pathway." (PMID 31998373, 2019). "VPS53 overexpression induces the autophagy signaling pathway, as exemplified by the increased expression of autophagy-related proteins, including LC3BII and Beclin 1, thus promoting autophagy and apoptosis and, in turn, impairing the proliferation, migration and invasion of colorectal cancer cells." (PMID 35805075, 2022).
epilepsy (2 papers, 2015 to 2016). A brain disorder characterized by episodes of abnormally increased neuronal discharge resulting in transient episodes of sensory or motor neurological dysfunction, or psychic dysfunction. "Also, mutations in the human VPS53 gene cause progressive cerebello-cerebral atrophy type 2 (PCCA2), a neurodegenerative disease characterized by severe mental retardation and early-onset epilepsy." (PMID 27191843, 2016).
anxiety disorder (1 paper, 2021). A category of psychiatric disorders which are characterized by anxious feelings or fear often accompanied by physical symptoms associated with anxiety. "The stop-strengthening variant in PMVK was associated with increased risk of Type 1 diabetes while the stop-strengthening variant in VPS53 was associated with a protective effect against anxiety disorders." (PMID 33750777, 2021).
cervical cancer (1 paper, 2019). A primary or metastatic malignant neoplasm involving the cervix. "VPS53, a component of the GARP complex involved in sphingolipid homeostasis, is a tumor suppressor in hepatocellular carcinoma; additionally, transfection with VPS53 transcript induces apoptosis and sensitizes cervical cancer cells to doxorubicin, consistent with our model." (PMID 31660150, 2019).
endometriosis (1 paper, 2018). The growth of functional endometrial tissue in anatomic sites outside the uterine body. "The differential expression protein VPS53 discovered in our study through iTRAQ technology can be used as a target for the treatment of endometriosis in the future." (PMID 30643524, 2018). "Our findings highlight a novel role for VPS53 in gynecology and provide a potent therapeutic strategy against endometriosis." (PMID 30643524, 2018). "Our results demonstrate that GZFLW can increase the expression of VPS53 through promoting its stability and induce the apoptosis of endometriosis stromal cells via mitochondria-induced apoptotic pathway." (PMID 30643524, 2018).
liver cancer (1 paper, 2023). An epithelial or non-epithelial malignant neoplasm that arises from the liver. "In addition, the homologous gene HCCS1 of VPS53 also has a strong anti-tumor effect on liver cancer cells." (PMID 37033223, 2023).
lung carcinoma (1 paper, 2022). "We determined its interaction with HindIII-digested chromatin fragments in a 45-kb region covering VPS53, FAM57A and GEMIN4 promoter regions in VCaP cells with ETH or DHT treatment and the lung cancer cell line A549." (PMID 36443337, 2022).
tumor (5 papers, 2011 to 2022). "Finally, to test the biological relevance of the 17p13.3 locus genes, we pursued tumor cellular assays to demonstrate the effect of VPS53, FAM57A and GEMIN4 on PCa cellular phenotypes." (PMID 36443337, 2022).
cancer (4 papers, 2011 to 2021). A tumor composed of atypical neoplastic, often pleomorphic cells that invade other tissues. "In the TCGA prostate cohort, cancer tissues displayed significantly higher expression levels for the VPS53 (p = 0.014), FAM57A (p = 0.013), and GEMIN4 (p = 1.2 × 10−5) genes in comparison to adjacent normal tissues." (PMID 34445492, 2021). "When explored in the TCGA Pan-Cancer tissues, all the 33 cancer types displayed a positive pairwise correlation between VPS53, FAM57A, and GEMIN4." (PMID 34445492, 2021). "Remarkably, the TCGA Pan-Cancer patients with a higher expression level of VPS53, FAM57A, and GEMIN4 also displayed decreased overall survival probability." (PMID 34445492, 2021). "Further studies in larger series of patients are warranted to elucidate this question and determine the specific role of those cancer associated genes (INPP5A, CDX1, MB, CAMK2A, APOL6 vs. VPS53, FAM57A, GEMIN4, SFRS13, ELP2P, GLOD4, CSF2RA and IL3RA), differentially altered in both groups of tumors." (PMID 21811587, 2011). "We then investigated the expression level of the three rs684232 target genes, VPS53, FAM57A, and GEMIN4, in cancer tissues and their effect on the clinical prognosis of cancer patients." (PMID 34445492, 2021). "Interestingly, for the 33 cancer types from the TCGA Pan-Cancer analysis project, up to 19, 16, and 16 cancer types displayed positive correlations for FOXA1 vs. VPS53, FOXA1 vs. FAM57A, and FOXA1 vs. GEMIN4, respectively." (PMID 34445492, 2021).
neurodegenerative disease (2 papers, 2015 to 2016). A disorder of the central nervous system characterized by gradual and progressive loss of neural tissue and neurologic function. "Compound heterozygous mutations of human VPS53 were reported recently to cause the neurodegenerative disease PCCA2." (PMID 26357016, 2015).
neurodevelopmental disorder (1 paper, 2023). A behavioral and cognitive disorder with onset during the developmental period that involves impaired or aberrant development of intellectual, motor, or social functions. "A report described a case of neurodevelopmental disorder resulting from an abnormality in Golgi-associated retrograde protein (GARP), of which VPS53 is a component, and was described to be associated with hip dislocation." (PMID 36902448, 2023).
neurological diseases (1 paper, 2016). "It will also be interesting to determine whether neurological diseases associated with VPS52 and VPS53 are caused by dysfunction of GARP or EARP or both." (PMID 27191843, 2016).
VPS53 also shares sentences with these, for which no sentence is quoted: benign prostatic hyperplasia (1 paper); Cerebellar atrophy (1); developmental delay (1); hepatocellular carcinoma (1); infection (1); Nystagmus (1); Onset (1); optic atrophy (1); pulmonary fibrosis (1); sarcoma (1); Type 1 diabetes (1).